CCND2 (cyclin D2)
Diseases named in the same sentence as CCND2 in open-access papers (continued):
Sharing a sentence is not in itself a finding about the gene and the disease.
prostate carcinoma (continued). "Thus, our study not only investigated the effects of the RTK/ERK pathway on the progression of prostate cancer, but also revealed the genetic factors responsible for aggressive disease susceptibility, highlighted the potential role of CCND2 in disease progression." (PMID 28674394, 2017). "The role of CA treatment on proliferative proteins (Cyclin-D1, CDK-2, Cyclin-D2) expression in prostate cancer cells PC-3 was examined by western blotting." (PMID 39574470, 2024). "Among these, CCND2, a member of the cyclin family regulating various cancer progressions, including prostate cancer, has garnered attention." (PMID 38994113, 2024). "One report showed that SMYD3 depletion reduced H4K20me3 level to upregulate CCND2 expression, whose restoration attenuated the hyperproliferative phenotype in prostate cancer LNCaP cells." (PMID 37386026, 2023). "SFN is capable of decreasing the expression of DNMT1 and DNMT3b and epigenetically modulating cyclin D2 expression, acting as a prostate cancer chemopreventive agent." (PMID 36235389, 2022). "Cyclin D2 is a major regulator of the cell cycle and its hypermethylation is correlated with prostate cancer progression." (PMID 36235389, 2022). "Another study also showed the arrest of the cell cycle in primary murine prostate cancer cells, due to the increased expression of cyclin D2, a known tumor suppressor protein." (PMID 35159343, 2022). "Recent reporter assays have shown that CCND2 is targeted by let-7a, and that this interaction inhibits proliferation in human prostate cancer cells both in vitro and in vivo." (PMID 30227870, 2018). "Reduced CCND2 expression promoted cell proliferation, and its overexpression inhibited prostate cancer cell growth." (PMID 30308939, 2018). "Silencing of the cell cycle regulatory gene cyclin D2 by promoter hypermethylation was reported to be positively correlated with prostate cancer progression, and restoration of cyclin D2 expression induced cancer cell death." (PMID 29977456, 2018). "Consistent with this, we found that overexpression of CCND2 in prostate cancer cell line LNCaP significantly inhibited its proliferation." (PMID 28674394, 2017). "This genetic study implicates the association of the SNPs rs3217869 (CCND2) and rs12643184 (PDGF-C), and the genes BAD, PDGF-D and CCND2 in the RTK/ERK signaling pathway with aggressive prostate cancer." (PMID 28674394, 2017). "Strikingly, CCND2 downregulation was consistently observed in the advanced prostate cancer in 18 available clinical data sets with a total amount of 1,095 prostate samples." (PMID 28674394, 2017). "This analysis revealed a marginal association between the RTK/ERK pathway genes including BAD (P = 0.058), PDGF-D (P = 0.051) and CCND2 (P = 0.052) and aggressive prostate cancer." (PMID 28674394, 2017). "In summary, our combined SNP- and gene-based analyses revealed the association of two novel loci (rs3217869/CCND2 and rs12643184/PDGF-C), and three genes (BAD, PDGF-D and CCND2) in the RTK/ERK signaling pathway with aggressive prostate cancer." (PMID 28674394, 2017). "To further assess the prognostic potential of CCND2 in prostate cancer and determine the relative dependency of PSA recurrence and overall survival, we performed multivariate analysis, including Gleason score, PSA levels, age and clinical T stage." (PMID 28674394, 2017). "We identified three genes BAD, CCND2, and PDGF-D with a marginal association with aggressive prostate cancer." (PMID 28674394, 2017). "Our preliminary results, obtained in a single-institution study with limited enrolment, showed that the hypermethylation of GSTP1, RARB, RASSF1, SCGB3A1 and CCND2 was highly tumour-specific in prostate cancer tissue." (PMID 27576364, 2016). "Although SCGB3A1 and CCND2 methylation in prostate cancer has been reported, the possibility of using these markers for the early diagnosis of PCa has never been fully investigated." (PMID 27576364, 2016).
prostate carcinoma (continued). "A high Cyclin D2 methylation levels was related with clinicopathologic features of tumor aggressiveness in prostate cancer." (PMID 27634882, 2016). "In prostate cancer, the frequency of CCND2 methylation status was much higher in prostate cancer samples than in non-malignant prostate tissues (p<0.005)." (PMID 27583477, 2016). "CCND2 had an inhibitory potential on the proliferation of androgen receptor (AR)-dependent prostate cancer cells." (PMID 27634882, 2016). "Our preliminary results highlighted that hypermethylation of GSTP1, RARB, RASSF1, SCGB3A1 and CCND2 was highly tumour-specific in prostate cancer tissue." (PMID 27576364, 2016). "By using qRT-PCR, cyclin D2 mRNA expression was determined in prostate cancer cells treated with SFN." (PMID 22303414, 2011). "Promoter hyper-methylation of cyclin D2, a major regulator of cell cycle, is correlated with prostate cancer progression, and restoration of cyclin D2 expression exerts anti-proliferative effects on LnCap prostate cancer cells." (PMID 22303414, 2011). "The present study was undertaken to evaluate the effects of SFN on the epigenetic regulation of cyclin D2 in prostate cancer cells." (PMID 22303414, 2011). "In prostate cancer, increased cyclin D2 promoter methylation corresponds to a decrease in cyclin D2 mRNA expression, and correlates with higher Gleason scores and pathologic features of tumor aggressiveness." (PMID 22303414, 2011). "Overall, we demonstrated the SFN induced up-regulation of cyclin D2 in prostate cancer cells, and examined SFN as an epigenetic modulator by altering methylation status in the cyclin D2 promoter region." (PMID 22303414, 2011). "Previous studies indicate that cyclin D2 promoter methylation is more extensive in malignant than nonmalignant human prostate tissue and treatment with 5-Aza-dC and TSA increased cyclin D2 expression in prostate cancer cell lines." (PMID 22303414, 2011). "Our preliminary experiments indicate that protein levels of both E2F2 and CCND2 are up-regulated in the PC3 prostate cancer cell line." (PMID 20418948, 2010). "The protein level of CCND2 is elevated in various prostate cancer cell lines." (PMID 38994113, 2024). "MiR-615 overexpression has been shown to suppress CCND2 mRNA and protein levels, inhibiting tumor progression, and restoration of Cyclin D2 expression partially reversed miR-615's inhibitory effects on prostate cancer cell proliferation, migration, and invasion." (PMID 38994113, 2024). "EGR1 binds to the cyclin D2 promoter and regulates its expression in prostate cancer cell lines." (PMID 39501082, 2024). "Moreover, SFN was able to decrease the expression of DNMT1 and DNMT3 in LnCap prostate cancer cells, as well as to reduce methylation in Cyclin D2 promoter, thus inducing Cyclin D2 gene expression in those cells." (PMID 36776295, 2023). "Moreover, short interfering RNA (siRNA)-mediated knockdown of CCND2 in prostate cancer cells DU145 greatly promoted cell growth and viability compared to the cells with negative control siRNAs." (PMID 28674394, 2017). "LINC00087 that competitively regulated VEGF and CCND2 suggested that it may play an important role in prostate cancer." (PMID 27634882, 2016). "As is reported in prostate cancer, CCND2 promoter methylation was more frequently observed in high Gleason score tumors and was associated with tumor development in prostate.However, the expression of CCND2 and the regulation mechanism underlying renal cell cancer has not been reported before." (PMID 27583477, 2016). "In addition, KCTD11 overexpressing prostate cancer cells displayed a reduction of cell proliferation-related genes, which are known direct targets of Hedgehog/Gli1, such as Cyclin D2 and IGF-2." (PMID 25045667, 2014).
prostate carcinoma (continued). "Hypermethylation of the CCND2 promoter is significantly higher in prostate cancers compared to normal prostate tissues (32%, 6% resp.; P = 0.004), and there are statistically significant concordances between methylation of CCND2 and the methylation of RARβ, GSTP1, CDH13, RASSF1A, and APC genes." (PMID 22191037, 2011). "In this study, we used in vitro and in vivo approaches to investigate whether E2F2 and CCND2 are direct targets of let-7a, and if let-7a acts as a tumor suppressor in prostate cancer by down-regulating E2F2 and CCND2." (PMID 20418948, 2010). "Additionally, the authors identified that SMYD3-depleted prostate cancer cells show S phase arrest, and this correlates with increased expression of cyclin D2 (CCND2), a key cell cycle regulator at the G1/S checkpoint that has been shown to be frequently silenced in prostate carcinomas." (PMID 33637115, 2021). "Interestingly, CCND2 was also identified as the target gene for miR-21, miR-182 (our study), let-7a (this study,) and miR-154, as differentially-expressed miRNA in prostate cancer." (PMID 32784653, 2020). "Additionally, it has already been proved that the overexpression of CCND2 inhibited cell growth of prostate cancer, whereas reduced expression promoted cell proliferation of PCa cells and was correlated with tumour progression to high Gleason score and elevated PSA levels." (PMID 32784653, 2020). "Our findings support the original hypothesis that methylation status of six selected index genes (HSPB1, CCND2, TIG1, DPYS, PITX2, and MAL) provides a novel, objective, and accurate prediction of death from prostate cancer in men clinically assessed as low to intermediate risk." (PMID 27708246, 2016). "Primary prostate carcinoma expression profiles also demonstrated SMYD3 overexpression and CCND2 downregulation." (PMID 33637115, 2021). "An experiment with LNCap prostate cancer cells showed that SFN treatment reduced the expression of DNMT1 and 3b, resulting in a decrease in the global DNA methylation profile and cyclin D2 promoter methylation." (PMID 29977456, 2018). "We identified five highly methylated genes in prostate cancer: GSTP1, RARB, RASSF1, SCGB3A1, CCND2 (P < 0.0001), with an area under the ROC curve varying between 0.89 (95 % CI 0.82–0.97) and 0.95 (95 % CI 0.90–1.00)." (PMID 27576364, 2016). "Methylation was quantified by pyrosequencing assays for six genes (HSPB1, CCND2, TIG1, DPYS, PITX2, and MAL) with established biomarker value in prostate cancer." (PMID 27708246, 2016). "In a recent report, we demonstrated that changes in methylation of HSPB1, CCND2, TIG1, DPYS, and, MAL, had significant prognostic effects in multivariate Cox models where death from prostate cancer was the study endpoint." (PMID 27708246, 2016). "Recently, it was reported that differential methylation of DPYS (and heat shock 27 kDa protein 1, HSPB1, OMIM: 602195 and cyclin D2, CCND2, OMIM: 123833) provides independent prognostic information for prostate carcinoma." (PMID 27733154, 2016). "Assays measuring methylation of MAL, TIG1, HSPB1, CCND2, and DPYS have potential to accurately stratify early prostate cancers and thereafter to manage affected patients in a biologically appropriate manner." (PMID 25193387, 2014). "Methylation of five candidate genes frequently silenced by methylation in breast and prostate cancer, including ER, RARβ2 and the cell cycle regulators p16, RASSF1 and CCND2 (cyclin D2) was analyzed in breast tissue." (PMID 25322458, 2014). "A recent study demonstrated that let-7a inhibits proliferation of human prostate cancer cells by targeting E2F2 and CCND2." (PMID 22363450, 2012).
prostate carcinoma (continued). "The appearance of known targets of methylation, CCND2, CD44, ECAD and GADD45A, demonstrated the success of this technique in identifying (potential) targets of methylation in prostate cancer." (PMID 17453001, 2007). "In recent years, several groups have reported the reduced or lack of expression of CCND2 in breast, lung and prostate cancers." (PMID 27583477, 2016). "In the comprehensive multivariate analysis, the model with best prognostic ability included Gleason score, PSA, HSPB1, [HSPB1xGleason score], CCND2 and DPYS demonstrating that gene methylation added significant information for predicting prostate cancer-related death." (PMID 25193387, 2014). "Moreover, the annotated genes in the constructed network, such as APC, AXIN1, AKT2, CCND2, CAV1, TLE2 and TCF4, are essential regulatory components of these pathways in prostate cancer." (PMID 23782521, 2013). "Our results demonstrated the ability of SFN to epigenetically modulate cyclin D2 expression, and provide novel insights into the mechanisms by which SFN may regulate gene expression as a prostate cancer chemopreventive agent." (PMID 22303414, 2011). "While no changes in H3K4 and H3K27 methylation marks were seen, there was a significant decrease in the H4K20me3 repressive mark in sh-SMYD3 prostate cancer cells, providing further evidence that SMYD3 expression may repress CCND2 expression via H4K20 tri-methylation in prostate cancer." (PMID 33637115, 2021). "Our results indicate that SFN may down-regulate DNA methyltransferases (DNMTs) resulting in de-methylation of the cyclin D2 promoter and de-repression of cyclin D2 expression, and suggest a novel mechanism behind SFN's growth inhibitory effects on prostate cancer cells." (PMID 22303414, 2011). "Furthermore, the lower expression levels of CCND2 markedly correlated with prostate tumor progression to high Gleason score and elevated PSA levels, and served as an independent predictor of biochemical relapse and overall survival in a large cohort of prostate cancer patients." (PMID 28674394, 2017). "However, multivariate analysis revealed that methylation of DPYS, CCND2 and HSPB1 together added a substantial amount of prognostic information not captured by any other measure and therefore may be useful for improvement of prostate cancer management." (PMID 25193387, 2014). "In the same study, over-expression of cyclin D2 induced anti-proliferative effects on LnCap cells, but not PC3 cells, suggesting that the inhibitory effects of cyclin D2 is limited to AR-dependent prostate cancer cells." (PMID 22303414, 2011).
gastric cancer (43 papers, 2003 to 2026). A primary or metastatic malignant neoplasm involving the stomach. "Conversely, other research indicates that low methylation of CCND2 is associated with increased CCND2 expression in advanced stages of gastric cancer." (PMID 40678058, 2025). "For example, in gastric cancer, some studies have CCND2 hypermethylation listed as an underlying cause of proliferation, whereas others have found CCND2 hypomethylation leading to increased CCND2 expression in more advanced-stage gastric carcinomas." (PMID 37510349, 2023). "We observed CCND2 overexpression in both CSC‐treated Beas‐2B cells and NSCLC cell lines, and studies have shown overexpression of CCND2 in gastric cancer that is associated with tumor progression and metastasis." (PMID 36621828, 2023). "Several studies have found that loss of CCND2 expression was observed in breast, lung, prostate, pancreatic and gastric cancer." (PMID 27583477, 2016). "Previous reports stated that promoter methylation of cyclin D2 was associated with transcriptional silencing in gastric cancer cell lines." (PMID 22303414, 2011). "Taken together, these results suggest that promoter hypermethylation is a major mechanism underlying the loss of cyclin D2 function in both gastric cell lines as well as in primary gastric cancer." (PMID 12771922, 2003). "Herein, we tested the association between cyclin D2 promoter hypermethylation and loss of cyclin D2 expression in gastric cancer." (PMID 12771922, 2003). "The same observation was also found in primary human gastric cancers in which the density of methylation appears to have an inverse association with the expression of cyclin D2." (PMID 12771922, 2003). "In tumor subgroup, CCND2 was associated with shorter OS in patients with gastric cancer (HR = 2.20, 95% CI: 1.66‐2.92), whereas it might be a tumor suppressor in NSCLC (HR = 0.28, 95% CI: 0.12‐0.64)." (PMID 30950241, 2019). "CCND2 is a crucial cell cycle-regulatory protein; its overexpression is described in several human neoplasms, including colorectal adenomas and gastric cancer, and it is associated with a poor prognosis in gastric cancer." (PMID 28382019, 2017). "BCL6 degradation caused by the HB-EGF-CTF also might induce cyclin D2 expression in human gastric cancers." (PMID 19337254, 2009). "Promoter hypermethylation of cyclin D2 with resultant loss of cyclin D2 may therefore have an antineoplastic effect on gastric cancer cells." (PMID 12771922, 2003). "On the basis of these results, we speculate that in undifferentiated gastric cancers, the degradation of BCL6 induces cell-cycle acceleration through cyclin D2 expression and that this cell-cycle acceleration might be associated with undifferentiated gastric cancers." (PMID 19337254, 2009). "CCND2 expression was suggested to be an independent prognostic factor for overall survival in patients with gastric cancer." (PMID 41516419, 2026). "Previous studies have demonstrated that disrupting CCND2 expression can inhibit the proliferation of gastric cancer cells, which heightens the significance and relevance of our research." (PMID 40708910, 2025). "This study showed that knockdown of lncRNA TTTY15 can down-regulate CCND2 expression by sponging miR-98-5p, thereby reducing gastric cancer progression." (PMID 35266852, 2022). "It has been reported, furthermore, that miR-101 suppresses the expression of CCND2 in H. pylori related to gastric cancer, which is in accordance with our results." (PMID 35741797, 2022). "TTTY15 knockdown inhibited gastric cancer cell proliferation but promoted apoptosis by sponging miR-98-5p, which acted as a tumor suppressor gene by reducing the expression of its target gene CCND2 in gastric cancer." (PMID 35266852, 2022). "Then, a series of functional experiments were conducted to verify that the miR-98-5p/CCND2 axis is involved in the regulation of gastric cancer progression." (PMID 35266852, 2022).